EZH2 (enhancer of zeste 2 polycomb repressive complex 2 subunit)
Diseases named in the same sentence as EZH2 in open-access papers (continued):
Sharing a sentence is not in itself a finding about the gene and the disease.
glioblastoma (continued). "Evidence showed that EZH2 could bind to Stat3, and the EZH2-Stat3 interaction led to enhance Stat3 activity in glioblastoma cells." (PMID 28360411, 2017). "Given that a large number of EZH2 targets in the regulation of metabolism and tumorigenesis, we hypothesized that the actions of EZH2 in glioblastomas may be related to HIF1α." (PMID 27259264, 2016). "Up-regulation of EZH2 in the glioblastoma cells promoted cell proliferation." (PMID 27259264, 2016). "Indeed, radioresistant glioblastoma multiforme (GBM) cell populations were sensitized to XRT by Enhancer of Zeste Homolog 2 (EZH2) inhibitors." (PMID 27384589, 2016). "Similarly, down-regulation of miR-101 in glioblastoma cells promotes their proliferation and invasion along with angiogenesis by increasing the EZH2-mediated overexpression of cytoplasmic polyadenylation element-binding protein 1 (CPEB1)." (PMID 27793053, 2016). "Additionally, by analyzing another data of EZH2 shRNA in human glioblastoma stem cell (GSE18150), we observed similar results." (PMID 26169043, 2015). "Similarly, this EZH2 phosphorylation allows the association with STAT3 promoting its methylation and activation in glioblastoma." (PMID 26580594, 2015). "EZH2 seems essential for glioblastoma cancer stem cell maintenance." (PMID 25255316, 2014). "Also, pharmacologic or genetic inhibition of EZH2 can prevent self-renewal and tumourigenicity of glioblastoma CSCs." (PMID 22771539, 2013). "While most studies have identified cancer-suppressing target–mostly cell cycle-associated–genes that are repressed by EZH2 through epigenetic silencing, few studies have shown tumor-promoting genes that are positively regulated by EZH2 such as c-myc in glioblastoma." (PMID 23077658, 2012). "In glioblastoma tissue we observed a strong EZH2 expression in perinecrotic areas." (PMID 23077658, 2012). "Finally, we show that inhibition of EZH2 histone methyltransferase activity inhibits vascularization in glioblastomas in vivo, suggesting a possible therapeutic potential for EZH2 inhibitors in the many diseases in which aberrant vacularization plays a role." (PMID 21297974, 2011). "EZH2 was reported to positively regulate MYC in glioblastoma cells." (PMID 21941025, 2011). "In addition, we analyzed EZH2 mRNA expression in glioblastoma blood vessel endothelial cells resected from patient samples." (PMID 21297974, 2011). "In addition, treatment with EZH2 siRNA and DZNep also inhibited growth factor- or glioblastoma-induced HBMVEC tubule network formation." (PMID 21297974, 2011). "Resultantly, a magnificentdual EZH2/HSP90 inhibitor was pinpointed that exerted striking cellgrowth inhibitory efficacy against TMZ-resistant Glioblastoma (GBM)cell lines." (PMID 38285511, 2024). "However, whether PRMT6 increases the invasiveness of glioblastoma cells by promoting the expression of EZH2." (PMID 39043634, 2024). "HCMV clinical strains transform HAs and fit with an HCMV-induced glioblastoma model of oncogenesis, and supports the tumorigenic properties of Myc and EZH2 which might be highly pertinent in the pathophysiology of astrocytic brain tumors and thereby paving the way for new therapeutic strategies." (PMID 37147437, 2023). "Moreover, it was previously shown that EZH2 suppression in glioblastoma shifts microglia towards the M1 phenotype, and the knockdown of EZH2 inhibited the expression of anti‐inflammatory factors while promoting the expression of pro‐inflammatory factors in glioblastoma cells." (PMID 34820775, 2022). "However, whether NF-κB regulates the malignant progression of glioblastoma through EZH2 is still unclear." (PMID 36263173, 2022). "It is notable that NF-κB can potentially cooperate with EZH2 in more than one way, and most importantly, we demonstrate a Synergistic effect of cancer cells induced by combinatory inhibition of NF-κB and EZH2, which both are frequently over-activated in glioblastoma." (PMID 36263173, 2022).
glioblastoma (continued). "Even in glioblastomas where EZH2 is overexpressed, prolonged depletion of Ezh2 results in a switch in cell fate that promotes tumor progression, suggesting that a careful regimen for treating tumors with EZH2 inhibitors should be considered to maximize the benefits." (PMID 35395831, 2022). "Finally, the potential tumorigenicity of glioblastoma cells may also be affected by recruitment of EZH2 (a subunit of the Polycomb Repressive Complex 2) to the NKD1 promoter by H19, with its repression positively contributing to glioblastoma tumorigenicity." (PMID 32283739, 2020). "Moreover, it has recently been described that MELK interacts with the transcription factor FOXM1 (a master regulator for cell proliferation) in a Plk-1-dependent manner and that EZH2-mediated radiation resistance occurs through a MELK-FOXM1-dependent manner in glioblastoma cells." (PMID 31740676, 2019). "However, the study of the HIF-EZH2 interplay is complicated by the observation that, in glioblastoma, EZH2 activates HIF-1α expression by inhibiting the eleven-nineteen lysine-rich leukemia associated factor 2 (EAF2) that, in the prostate, regulates transcriptional elongation of RNA Poll II." (PMID 30510924, 2018). "Moreover, down-regulation of EZH2 in glioblastoma leads to cell cycle arrest at the G0/G1 phase." (PMID 27793053, 2016). "Phosphorylation of EZH2 at serine 21 was found to be highly expressed in stem-like cells of glioblastoma multiforme, and this phosphorylation by protein kinase B (AKT) signaling facilitates STAT3 methylation by EZH2, thus enhancing STAT3 activity." (PMID 40028035, 2025). "In glioblastoma, lncRNA AGAP2-AS1 recruits lysine-specific histone demethylase 1 (LSD1) and enhancer of zeste homolog 2 (EZH2) to the TFPI2 promoter, leading to H3K27me3 and DNMT1-mediated methylation, silencing TFPI2 and promoting tumor progression." (PMID 40361374, 2025). "We transfected the small interfering RNA targeting TRAF6 into PRMT6-silenced glioblastoma cells to achieve re-inhibition of TRAF6, and subsequently observed an upregulation of EZH2 expression." (PMID 39043634, 2024). "These rescue experimental results indicate that EZH2 can restore the invasion and migration abilities of glioblastoma cells deprived of PRMT6, that is, PRMT6 induces glioblastoma cell invasion and migration via EZH2." (PMID 39043634, 2024). "In glioblastoma stem cells (GSCs), co-immunoprecipitation experiments revealed that STAT3 co-precipitated not only with EZH2 but also with SUZ12 and EED, which are core components of PRC2." (PMID 38534385, 2024). "In glioblastoma, poorer overall survival was noted among patients with higher expression levels of MELK and EZH2." (PMID 38183103, 2024). "Nonetheless, EZH2 and MELK cooperate in glioblastoma and medulloblastoma to promote cell proliferation and this interplay offers a potential combination therapeutic strategy." (PMID 38183103, 2024). "In experiments involving PRMT6-depleted glioblastoma cells treated with a proteasome inhibitor (MG132), an increase in EZH2 protein expression was observed." (PMID 39043634, 2024). "The relationship between EZH2 and PTEN highlights critical insights into the origins of aberrant signaling in glioblastoma and considerations for therapy." (PMID 38183103, 2024). "The histone lysine N-methyltransferase EZH2 is a component of the Polycomb Repressive Complex 2 (PRC2), has been extensively researched in several cancers, including Glioblastoma and MB." (PMID 36968588, 2023). "For example, cancer-related proteins such as EZH2 and c-Met, as well as the glucose transporter GLUT1, have been reported to be S-palmitoylated and stabilized to promote glioblastoma cell growth." (PMID 37712874, 2023). "In line with EZH2 and HCMV involvement in our glioblastoma model, combination triple therapy (GSK343/GCV/TMZ) curtailed the growth of CEGBCs-derived spheroids." (PMID 37147437, 2023).
glioblastoma (continued). "Given that glioblastoma is highly heterogenous with distinct subtypes, combined inhibition of BMI1 and EZH2 provide much stronger anti‐tumour efficacy than targeting each one alone." (PMID 35851726, 2022). "The last hub lncRNA NEAT1 promotes glioblastoma development and progression through the EGFR/NEAT1/EZH2/WNT/β-catenin axis." (PMID 36090045, 2022). "EZH2 binds and methylates STAT3 at K180 and enhances STAT3 tyrosine phosphorylation in glioblastoma, possibly by protecting it from dephosphorylation." (PMID 35795677, 2022). "In glioblastoma, markers of tumor progression include the expression of proliferating cell nuclear antigen (PCNA), enhancer of zeste homolog 2 (EZH2) and ionic transporters that regulate intracellular chloride levels." (PMID 35216113, 2022). "The proliferation results indicated that the EZH2 inhibitor EPZ-6438 synergised with the NF-κb inhibitor CAPE in inducing anti-proliferative activities in both LN229 and U251 glioblastoma cell lines." (PMID 36263173, 2022). "Histone modification by polycomb repressive complex 2, through its catalytic subunit EZH2, induces the epigenetic silencing of the BMPR1B/ALK6 gene, leading to escape from the BMP‐induced differentiation of glioblastoma cells." (PMID 34214250, 2022). "Emerging evidences indicate that EZH2 is indispensable for BCSC proliferation and its specific silencing inhibits glioblastoma multiforme CSC self-renewal in vitro and tumor-initiating capacity in vivo." (PMID 36273585, 2022). "Studies have also reported that EZH2 is involved in a novel miR-490-3p/TGIF2/TGFBR1 axis inducing migration and EMT in glioblastomas." (PMID 36230759, 2022). "PCNA and EZH2 marker assays of PBT24 and SF8628 glioblastoma tumors transplanted on CAM showed that the PBT24 tumor is less aggressive than the SF8628 tumor." (PMID 35216113, 2022). "Some research show that EZH2 inhibition leads to significant reduction of M2 markers (CD206) and elevation of M1 markers (TNFα and iNOS) in TAMs co-cultured with murine glioblastoma cells." (PMID 36038549, 2022). "Their core members such as EZH2 and BMI1 seem to divide their work in the PN and MES subtype of glioblastoma." (PMID 35851726, 2022). "Of note, a previous study has shown that EZH2 methylates STAT3 and enhances the Y705 phosphorylation and activity of STAT3 in glioblastoma cells." (PMID 33868295, 2021). "Protein kinase B (PKB)/AKT-induced pS21 EZH2 was capable of accelerating EZH2-STAT3 intercommunication, stimulated EZH2-mediated STAT3 methylation, and augmented STAT3 activity in glioblastoma multiforme (GBM) stem-like cells (GSCs)." (PMID 34745848, 2021). "METTL3 depletion affects the glioblastoma stem cell features via promoting nonsense‐mediated mRNA decay (NMD) of histone modifiers, such as EZH2." (PMID 34586728, 2021). "Other investigators noted that in glioblastoma, lncRNA NEAT1 bound to the histone methyltransferase enhancer of zeste homolog 2 (EZH2) and subsequently inhibited the expression of its downstream target genes." (PMID 33901015, 2021). "In glioblastoma, the research suggested that miR-708 affects glioblastoma cell proliferation, invasion, and apoptosis through regulating AKt1, CCND1, MMP2, EZH2, Parp-1 and Bcl219." (PMID 33028966, 2020). "To further examine the binding site of E2F7 in EZH2 promoter, we performed a ChIP-qPCR analysis to locate the E2F7-binding site on EZH2 promoter in glioblastoma cells." (PMID 32814835, 2020). "In glioblastoma stem-like cells (GSC), Akt-induced pS21-EZH2 can facilitate EZH2-STAT3 interaction, enhancing EZH2-mediated methylation and activity of STAT3, which accelerates GSC self-renewal and glioblastoma tumor progress." (PMID 32448308, 2020). "We found that EZH2 epigenetically silenced miR-9, which directly targets the oncogenic signaling of CXCR4 in glioblastoma cell lines." (PMID 32635336, 2020).
glioblastoma (continued). "Each one of these miRs targets several transcriptional regulators, including the oncogenic chromatin repressors EZH2, BMI1 and LSD1, which are functionally interdependent and involved in glioblastoma recurrence after therapeutic chemoradiation." (PMID 30683859, 2019). "Primary patient-derived glioblastoma cells expressed higher levels of HOTAIR and EZH2 compared with N33 cells." (PMID 31367244, 2019). "Several studies showed that EZH2 overexpression enhances chemoresistance in small cell lung cancer, head and neck squamous cell carcinoma (HNSCC) and glioblastoma." (PMID 29556394, 2018). "There is increasing evidence that EZH2 promotes angiogenesis in clear renal cell carcinoma, inflammatory breast cancer, nasopharyngeal carcinoma (NPC) and glioblastomas (GBM)." (PMID 28410242, 2017). "There was less information available for these mutual feedback regulatory axis; one study showed that regulation of EZH2 was involved in positive feedback loop with β-catenin/transcription factor 4 (TCF4) and Stat3 signaling in glioblastoma cells." (PMID 28360411, 2017). "Another study proved that EZH2 was able to directly bind to and methylate STAT3, thereby promoting the tumorigenicity of glioblastoma and prostate CSCs." (PMID 28415635, 2017). "As an epigenetic gene, EZH2 has only been reported to regulate in HCC cells and glioblastoma multiforme." (PMID 27706111, 2016). "Indeed, in the case of glioblastoma (GBM), although EZH2 is very frequently overexpressed, only its short-term inhibition ameliorates survival, while a longer depletion exacerbates tumour-related dedifferentiation." (PMID 26923714, 2016). "EZH2-dependent histone H3K27 trimethylation and DNA methylation via DNMTs have been found to lead to a cascade of events involving several coding and noncoding regions that ultimately result in glioblastoma aggressiveness." (PMID 39513112, 2024). "Targeting oncogenic chromatin repressors such as EZH2 (Enhancer of zeste 2 polycomb repressive complex 2 subunit), BMI-1, and SUZ12, the cooperative strategy of these microRNAs disrupts critical survival mechanisms in glioblastoma cells and unveils promising therapeutic avenues." (PMID 38419943, 2024). "EZH2 has been shown to be regulated by PRMT1, CARM1, and PRMT5, while whether PRMT6 is a regulator of EZH2 in glioblastoma is the subject of further investigation." (PMID 39043634, 2024). "Furthermore, the interaction between NEAT1 and EZH2 triggers trimethylation of H3K27, which activates the WNT/β-catenin pathway, thereby increasing the malignancy of glioblastoma." (PMID 39043634, 2024). "Additionally, rescue experiments demonstrated that PRMT6 enhances glioblastoma cell invasion and migration by modulating TRAF6-mediated EZH2 expression." (PMID 39043634, 2024). "The interaction between EZH2 and STAT3 has also been reported in glioblastoma and colon carcinomas." (PMID 37664059, 2023). "Given the stated EZH2 oncogenic functions, we aimed to evaluate the presence of a potential link between the triad of HCMV, CEGBCs and EZH2, as well as the potential interrelation with Myc in the context of glioblastoma carcinogenesis." (PMID 37147437, 2023). "In glioblastoma multiforme (GBM), which is often treated with concurrent chemoradiotherapy with temozolomide, EZH2 binds to and methylates STAT3, leading to enhanced STAT3 activity by phosphorylation of STAT3 and promoting the tumorigenicity of GBM stem-like cells." (PMID 37121970, 2023). "In glioblastoma, it has been shown that EZH2 promotes lipid synthesis and the accumulation of fatty acid mediated thorough the activation of PGC-1α via the interaction between EZH2 and the mutant telomerase reverse transcriptase (TERT)." (PMID 36135315, 2022). "Our results indicated that LPS, a potent activator of NF-κB, can significantly enhance proliferation and migration in control glioblastoma cells but not in EZH2-KO cells." (PMID 36263173, 2022).
glioblastoma (continued). "In glioblastoma, NF-κB activates global methylation of H3K27 through EZH2." (PMID 36263173, 2022). "In glioblastoma, however, it is the canonical NFκB signalling (rather than the non-canonical) that is constituvely activated to drive EZH2 expression and tumour progression." (PMID 36263173, 2022). "Our results have shown that NF-κB depletion sensitizes EZH2 inhibitors to reducing glioblastoma cell viability, an observation that has not been described previously." (PMID 36263173, 2022). "EZH2 can also methylate STAT3 and increase its activity in glioblastoma stem cells." (PMID 36612203, 2022). "In glioblastoma, AGAP2-AS1 could epigenetically silence TFPI2 expression by binding to EZH2 and LSD1 to promote GBM." (PMID 33815468, 2021). "Moreover, EZH2 regulates lipid metabolism through the EZH2-TERT-lipid metabolism network, with EZH2 knockdown glioblastoma cells showing reduced fatty acid synthase expression and resultant diminished fatty acid levels." (PMID 34947882, 2021). "EZH2 binds and methylates STAT3 to promote tumorigenicity of glioblastoma." (PMID 32477007, 2020). "In addition, based on the analysis of glioblastoma patient specimens, we found that EZH2 expression was positively correlated with E2F7, and high expression of EZH2 was correlated with poor patient prognosis." (PMID 32814835, 2020). "Furthermore, ICG-Gen@CasNPs/PDT/PTT directed ubiquitination and proteasomal degradation of EZH2 and BMI1 indicates the implication of the polycomb in conferring glioblastoma survival." (PMID 36131972, 2019). "Here we, hypothesyze that in glioblastoma H19 exerts its function through the interaction with the catalytic subunit of the PRC2 complex, EZH2." (PMID 29643989, 2018). "The phosphorylated EZH2 directly binds to and methylates STAT3, leading to enhanced STAT3 activity by increasing phosphorylation of STAT3 at Y705 and thereby promotes the tumorigenicity of glioblastoma and glioblastoma stem-like cells (GSCs)." (PMID 29556394, 2018). "The phosphorylated EZH2 also can directly bind to and methylate STAT3, leading to enhanced STAT3 activity by increased tyrosine phosphorylation of STAT3 and thereby promote the tumorigenicity of glioblastoma stem-like cells (GSCs)." (PMID 29556394, 2018). "The non-classic role of EZH2 was validated in glioblastoma CSCs and liver CSCs, in which EZH2 exerts its role through STAT3 and β-catenin methylation." (PMID 30310855, 2018). "What's more, EZH2 could upregulate STAT3 activity by methylating STAT3, leading to glioblastoma stem-like cells (GSCs) formation, further to sustain the stemness of GSCs." (PMID 27880940, 2017). "In principle, all miRNA interfering with the histone methyltransferase EZH2 can be considered as tumor suppressors, in particular let-7 which inhibits also oncogenes like MYC and K-RAS and is capable of inhibiting glioblastoma cell proliferation." (PMID 29234674, 2017). "Similarly, AKT1 phosphorylates EZH2 and induces the expression of STAT3 in glioblastoma with stem-like cells promoting tumorigenicity." (PMID 27793053, 2016). "This is associated with β-catenin/TCF4 and STAT3 downregulation, which can, in turn, suppress EZH2 expression representing a negative feedback loop that is deregulated in glioblastoma leading to uncontrolled cell cycle progression." (PMID 27793053, 2016). "In addition, EZH2 phosphorylation activates STAT3 signaling via STAT3 methylation and promotes the tumorigenicity of glioblastoma stem-like cells." (PMID 25428914, 2015). "Moreover, phosphorylation EZH2 binds to and methylates STAT3, thereby enhancing STAT3 activity, which promotes tumorigenicity of glioblastoma stem-like cells." (PMID 24345883, 2013).